INS (insulin)
Diseases named in the same sentence as INS in open-access papers (continued):
Sharing a sentence is not in itself a finding about the gene and the disease.
Hyperglycemia (continued). "In T2DM patients, insulin cannot regulate hepatic glycogen synthesis or glucose production, and increased hepatic gluconeogenesis is the primary cause of fasting hyperglycemia in T2DM." (PMID 40722684, 2025). "Hyperglycemia and disrupted brain insulin signaling, known risk factors for AD onset, are associated with altered d‐Ser metabolism, as AD‐linked low insulin responsiveness affects d‐Ser regulation." (PMID 40146632, 2025). "T2D is a heterogeneous disorder characterized by hyperglycemia and caused by multiple pathophysiologic pathways with contributions of insulin insensitivity or resistance and pancreatic beta cell dysfunction among subgroups and individuals." (PMID 39859066, 2025). "This sustained inflammatory environment subsequently was reported to impair cellular responses to insulin, favouring a state of systemic insulin resistance intricately associated with dyslipidemia and hyperglycaemia." (PMID 41226484, 2025). "Continuous data from CGMs enable more accurate insulin dosing decisions, potentially reducing both hypoglycemia and hyperglycemia risk." (PMID 41002329, 2025). "T2DM represents a group of metabolic disorders characterized by hyperglycemia, primarily caused by inadequate insulin secretion or resistance to insulin." (PMID 40106408, 2025). "For T1D, protein-rich meals often cause delayed hyperglycemia, requiring tailored insulin strategies and CGM oversight." (PMID 41305580, 2025). "In those algorithms, marked hyperglycemia at diagnosis (HbA1c ≥ 10% or Fasting Plasma Glucose ≥ 300 mg/dL) or symptomatic hyperglycemia (polyuria, polydipsia, weight loss) are referred to as barometers of insulin initiation." (PMID 40710394, 2025). "Following the intervention, insulin administration caused a marked decrease in glucose levels in the experimental group, while sham procedures induced stress-related hyperglycemia in controls." (PMID 40362391, 2025). "Hyperglycemia results from metabolic defects causing deficits in insulin secretion, insulin action, or both." (PMID 40244115, 2025). "Diabetic cats with posthypoglycemic hyperglycemia or hypersomatotropism exhibit higher GV, which is associated with higher insulin doses, elevated fructosamine concentrations, and poorer glycemic control." (PMID 40853201, 2025). "This production is caused by pathway-specific insulin resistance, meanwhile, triggering intracellular hyperglycemia and vascular damage." (PMID 41293734, 2025). "Clinical onset occurs after the loss of 80–90% of beta-cell mass, resulting in hyperglycemia and the need for lifelong insulin therapy." (PMID 40906116, 2025). "Subcutaneous insulin therapy requires continuous glucose monitoring and multiple daily injections, often causing pain, poor compliance, and risks of hyperglycemia or hypoglycemia." (PMID 41463606, 2025). "Key mechanisms linking T2DM and AD include hyperglycaemia, which damages cerebral blood vessels and impairs blood flow, and insulin resistance, which promotes tau phosphorylation, a hallmark of AD." (PMID 39899444, 2025). "Hyperglycemia causes an increase in advanced glycation end products that contribute to inflammatory and oxidative stress pathways, but also interfere with insulin signaling." (PMID 40429969, 2025). "It was now clear that further hypoglycaemia was unlikely, and the patient’s main risk was from hyperglycaemia so P31 restarted the patient’s insulin at a slightly reduced dose, which they subsequently increased." (PMID 40973362, 2025). "Intriguingly, the carboplatin/5-FU rats in the Drug group exhibited a decrease in blood glucose levels, a finding that diverges from the anticipated chemotherapy-associated hyperglycemia often attributed to impaired insulin production." (PMID 41372700, 2025). "Hyperglycemia is a risk factor for the onset of AD, and impaired brain insulin signaling is known to occur in the disease." (PMID 40146632, 2025).
Hyperglycemia (continued). "After eating, insulin secretion increases, and glucagon secretion is inhibited by the combined actions of hyperinsulinemia and hyperglycemia caused by incretin hormones." (PMID 41012462, 2025). "Due to its high variability of action, NPH insulin is associated with a higher risk of both hypoglycemia and hyperglycemia compared to modern insulin analogues." (PMID 40574081, 2025). "For patients with PHG, intravenous insulin infusion was performed according to the institution's protocol, and perioperative risk factors for hyperglycemia and clinical outcomes were assessed." (PMID 40260105, 2025). "In contrast, protein- and fat-rich meals can cause delayed postprandial hyperglycemia in T1D, which requires a balanced insulin regimen such as split or extended boluses guided by CGM." (PMID 41305580, 2025). "Both insulin-dependent and non-insulin-dependent DM are associated with a significantly increased risk of impaired fracture healing, likely due to hyperglycemia-induced inflammation and fracture instability." (PMID 40870403, 2025). "Hyperglycemia alerts are rather helpful in young children with a greater risk of diabetic ketoacidosis, for insulin pump users, and for patients with good glycemic control who want to further ameliorate glycemic parameters." (PMID 41462808, 2025). "The autoimmune destruction of pancreatic β-cells leading to inadequate insulin production, along with the body's cells developing resistance to insulin, are the main contributors to the persistent hyperglycemia associated with DM." (PMID 40904960, 2025). "HD develops when liver disease—particularly cirrhosis—disrupts this axis, leading to insulin resistance and pancreatic β-cell dysfunction, ultimately causing hyperglycemia." (PMID 41462693, 2025). "This worsens insulin signaling, making impaired hepatic glucose uptake the main cause of hyperglycemia in cirrhotic patients." (PMID 40566506, 2025). "This personalized adjustment significantly reduces the occurrence of hypoglycemia or hyperglycemia episodes caused by inadequate insulin dosing." (PMID 41477679, 2025). "Increased ROS suppress GLUT-4 levels and exacerbate the tissue’s hyperglycemia and hyperinsulinemia, which cause desensitization of peripheral tissues to insulin." (PMID 40143138, 2025). "Patients usually present with marked hyperglycemia, often more than 800–1000 mg/dL, but only mildly elevated HbA1c levels, further suggesting the near-total and acute loss of insulin production." (PMID 41010821, 2025). "Traditional insulin dosing algorithms focus primarily on carbohydrate counting, often failing to adequately compensate for delayed hyperglycemia caused by prolonged digestion and metabolic conversion of protein and fat." (PMID 41156539, 2025). "This infection caused a recurrence of significant hyperglycemia and an increase in her insulin requirements." (PMID 40860576, 2025). "Postprandial hyperglycemia is due to decreased levels of blood insulin or action caused by reduced utilization of glucose in peripheral tissues." (PMID 39859258, 2025). "Poor sleep quality can lead to hormonal imbalances that affect insulin sensitivity and glucose metabolism, thereby increasing the risk of hyperglycemia." (PMID 40043024, 2025). "These risk factors included a previous hyperglycemia visit within the past month, age < 25 years, initial blood glucose < 20 mmol/L, having a family physician, and being on insulin." (PMID 40859828, 2025). "Astonishingly, the protein level of insulin was significantly increased in both of the long-term hyperglycemia groups, implying that the inactivation of Akt is caused by insulin resistant instead of insulin deficiency." (PMID 40054691, 2025). "We also report that in Lepob/ob mice, normalization of hyperglycemia by AgRP neuron inactivation was associated with markedly decreased plasma insulin levels." (PMID 40371641, 2025).
Hyperglycemia (continued). "An increase in fasting glucose is due to the liver producing more glucose and a reduction in early insulin secretion, whereas postprandial hyperglycemia is primarily caused by peripheral insulin resistance." (PMID 41234487, 2025). "Peri‐liver transplant hyperglycemia can be attributed to several factors, including post‐reperfusion hepatocyte injury, insulin resistance stemming from underlying liver disease, surgical stress, and the use of immunosuppressive drugs." (PMID 40931439, 2025). "As SST reduces insulin secretion, the long-acting use of SSTAs can cause hyperglycemia and negatively affect systemic glucose metabolism." (PMID 40427747, 2025). "The presence of insulin autoantibodies (IAA) in the blood causes postprandial hyperglycaemia to persist for longer because insulin bound to IAA is physiologically inactive, incapable of lowering blood glucose." (PMID 41349642, 2025). "Ulva lactuca polysaccharides mitigate aging-associated hyperglycemia in diabetic mice by reshaping gut microbiota composition and promoting the production of SCFAs, which enhance insulin signaling and suppress systemic inflammation." (PMID 40959703, 2025). "T2D is characterized by a relative deficiency of insulin, which ultimately results in progressive hyperglycemia." (PMID 40507585, 2025). "Elevated prolactin levels have been associated with a compensatory increase in insulin response to hyperglycemia and are also associated with improved insulin sensitivity." (PMID 39860463, 2025). "In mice with pancreatic β cell IL-22RA1 deficiency, hyperglycemia, defective insulin secretion, impaired glucose tolerance, and decreased insulin quality are observed." (PMID 40243151, 2025). "In the case of diabetic pregnant women, if glycemic control is poor, hyperglycemia will occur, which in turn will cause an increase in circulating glucose in the fetal plasma and the subsequent hypersecretion of insulin by the pancreas of that fetus." (PMID 40004100, 2025). "Mouse knockout of β-cell-specific Atg7 reduces β-cell mass, caused mild ER stress and hyperglycemia and reduced pancreatic insulin levels." (PMID 40141412, 2025). "In several trials, insulin was introduced within the first 6 weeks post-transplant as part of a preventive “β-cell rest” approach aimed at mitigating early postoperative hyperglycemia and reducing the risk of persistent PTDM." (PMID 40995094, 2025). "As postprandial hyperglycemia occurs earlier than fasting hyperglycemia during T2D development, it is important to assess all phases of insulin secretory capacity in predicting the risk of T2D." (PMID 39921368, 2025). "Conversely, in the BTBRob/ob group, islet cell hypertrophy was associated with increased body weight and hyperglycemia, which led to a reduced insulin-staining area due to sustained islet cell apoptosis and insulin resistance." (PMID 40394690, 2025). "T2D is characterized by chronic hyperglycemia emanating from deficiencies in insulin production, insulin action, or both." (PMID 39857685, 2025). "T2DM is characterized by hyperglycemia, caused primarily by defects in insulin secretion by the β‐cells of the pancreas and resistance of the target tissues to the effects of insulin." (PMID 39980831, 2025). "Excessive FMO3 activity has been linked to hyperglycaemia and hyperlipidaemia, while its suppression is associated with improved insulin sensitivity in insulin-resistant mice." (PMID 41154691, 2025). "T2DM consists of a variety of physical dysfunctions predominantly characterised by hyperglycaemia and caused by a combination of resistance to the action of insulin and/or the inadequate secretion of insulin." (PMID 41333512, 2025). "DM is a heterogeneous metabolic disorder characterized by chronic hyperglycemia caused by impaired insulin secretion, defective insulin action, or a combination of both." (PMID 41598218, 2025).
Hyperglycemia (continued). "According to the American Diabetes Association (ADA) guidelines, insulin therapy should be initiated in hospitalised patients with persistent hyperglycemia when blood glucose levels exceed 180 mg/dL on two occasions." (PMID 40931439, 2025). "Based on the presented results, it can be concluded that a single high dose of MH causes transient hyperglycemia and a decrease in insulin levels, while its chronic administration leads to a reduction in both blood glucose and insulin concentrations." (PMID 41515170, 2025). "Severe SARS-CoV-2 infection and its associated hyperinflammation and cytokine activation affect insulin target tissues (primarily the liver, muscle and adipose tissue), reducing insulin sensitivity and causing hyperglycemia." (PMID 40469441, 2025). "Previous studies demonstrated that STZ-induced long-term (>40 days) hyperglycemia caused tau phosphorylation through activating glycogen synthase kinase 3 beta (GSK3β), due to the deficiency of insulin and subsequent inactivation of Akt in brain." (PMID 40054691, 2025). "Foods with a lower GI, such as legumes, whole grains, and fiber-rich vegetables, are recommended to improve insulin sensitivity and reduce the risk of hyperglycemia." (PMID 40026940, 2025). "Insulin resistance, characterized by diminished cellular responsiveness to insulin, impairs glucose uptake while permitting unrestrained lipolysis, thereby promoting hyperglycemia and dyslipidemia, which underlie T2DM pathogenesis." (PMID 40723361, 2025). "Streptozotocin (STZ)-induced diabetic rats, untreated with insulin, exhibit human-like symptoms such as hyperglycemia, polydipsia, polyuria, weight loss, cardiomyopathy, neuropathy, and oxidative stress." (PMID 40143095, 2025). "Diabetes mellitus, a systemic condition with a rapidly increasing global prevalence, is defined by persistent hyperglycemia caused by insulin resistance (IR) and/or impaired insulin secretion." (PMID 40659888, 2025). "The flat pharmacodynamic profile of Gla-300 further minimizes fluctuations in blood glucose levels, reducing the risk of both hyperglycemia and hypoglycemia rendering steady insulin levels." (PMID 40190894, 2025). "Persistent hyperglycemia is a hallmark of DM caused by insufficient insulin secretion by pancreatic beta cells, the inability of peripheral tissues to effectively utilize insulin, or a combination of both." (PMID 40700168, 2025). "This was a highly important observation, as fasting hyperglycaemia is caused by relatively unrestrained hepatic glucose production despite high fasting plasma insulin levels." (PMID 40316731, 2025). "The cellular mechanisms behind weight gain are not fully understood, but it is well-known that this agent can cause hyperglycemia (insulin resistance) and hyperlipidemia through different mechanisms discussed in this review." (PMID 41303162, 2025). "Factors such as surgical trauma, anesthesia, and blood loss can trigger the secretion of significant amounts of insulin antagonistic hormones in the body, such as adrenal corticosteroids, cortisol, and catecholamines, leading to stress-induced hyperglycemia." (PMID 41426576, 2025). "In patients with T2D, insulin injections have become the main clinical treatment and efficiently reduce hyperglycemia; however, these treatments frequently carry a risk of dysregulation of glucose metabolism." (PMID 39996734, 2025). "T2DM is a chronic metabolic disorder with hyperglycemia, caused by defective insulin secretion by pancreatic β-cells and the inability of insulin-sensitive tissues to respond appropriately to insulin." (PMID 39847072, 2025). "This disruption leads to a progressive decline in insulin production and, thus beta-cell function, ultimately culminating in insulin deficiency and the onset of hyperglycemia." (PMID 40305339, 2025).
Hyperglycemia (continued). "IL-22 released by ILC3 cells protected pancreatic islet beta cells from inflammation and glucotoxicity, potentially reversing the damage caused by hyperglycemia to pancreatic islet beta cells, thus improving insulin sensitivity." (PMID 39944639, 2025). "Corticosteroids, especially systemic variants, are recognized for inducing hyperglycemia by enhancing hepatic gluconeogenesis, diminishing insulin sensitivity, and obstructing glucose absorption by peripheral organs." (PMID 40142617, 2025). "It is a metabolic disorder characterized by inadequate insulin secretion from the pancreas and abnormal insulin levels, causing microvascular complications and hyperglycemia." (PMID 40723948, 2025). "This disturbance of insulin signaling decreases uptake of glucose by cells due to DM, causing increased, prolonged blood glucose levels, called hyperglycemia." (PMID 39859258, 2025). "In a metabolic syndrome model, the GLP-1 receptor agonist exendin-4 was given to hyperglycemia mice, resulting in sustained plasma glucose reduction, weight loss, and enhances insulin sensitivity over multiple weeks of treatment." (PMID 40625678, 2025). "We describe for the first time in this infant population that male sex is associated with longer time spent in hyperglycemia and insulin treatment during the admission period is associated with longer time spent in hypoglycemia nearing term age." (PMID 40576801, 2025). "Conditional inactivation of Nkx6.1 in β-cells of adult mice is associated rapid-onset glucose intolerance, hyperglycemia, and reduced circulating insulin; accompanied by reductions in genes associated with insulin-secretion and β-cell proliferation." (PMID 40134803, 2025). "IR leads to reduced insulin sensitivity, causing persistent hyperglycemia and higher glycosylation levels." (PMID 41169465, 2025). "To compensate, pancreatic β-cells initially increase insulin production; however, this compensatory response becomes insufficient over time, leading to relative insulin deficiency and hyperglycemia." (PMID 40564201, 2025). "Smoking not only causes chronic inflammation that directly contributes to COPD, but also reduces insulin action causing hyperglycaemia in the body which indirectly leads to decreased lung function." (PMID 39917066, 2025). "Impaired insulin sensitivity and beta-cell dysfunction are believed to underlie the association between depression and hyperglycemia, further increasing the risk of MetS." (PMID 40432661, 2025). "Overproduction of ROS, a common feature of a chronic hyperglycemia environment, is the consequence of a deficiency and/or resistance to insulin in PGDM." (PMID 41237113, 2025). "This typically involves reducing bolus insulin before Iftar (the evening meal) and/or adjusting basal insulin to minimize hypoglycemia risk, with careful monitoring of post—Iftar glucose to avert hyperglycemia." (PMID 40364253, 2025). "In T1DM, the immune system mistakenly attacks and destroys insulin-producing β cells, resulting in their loss and subsequently hyperglycemia due to insufficient insulin production." (PMID 40076814, 2025). "Adiponectin also reduces hepatic glucose production and enhances peripheral glucose and fatty acid utilization, thereby improving insulin sensitivity and countering hyperglycemia, both critical risk factors for vascular disease." (PMID 40565591, 2025). "We recruited pregnant women with ≥1 risk factor to a prospective observational cohort study of pregnancy hyperglycaemia, endocrine causes, lipids, insulin and autoimmunity (OPHELIA), from nine UK centres." (PMID 39687981, 2025). "Imatinib and dasatinib, for instance, have been linked to modest improvements in hyperglycemia, potentially through mechanisms involving elevated adiponectin levels and enhanced insulin sensitivity." (PMID 40292250, 2025).